VMP1 (vacuole membrane protein 1)
Diseases named in the same sentence as VMP1 in open-access papers (continued):
Sharing a sentence is not in itself a finding about the gene and the disease.
pancreatitis (continued). "VMP1 autophagic vesicles are present in the pancreas of rats submitted to experimental pancreatitis, showing that VMP1 is involved in the induction of autophagy during the disease." (PMID 22550490, 2012). "Aberrant expression or dysfunction of VMP1 has been reported in various pathological conditions—including neurodegenerative disorders like Parkinson’s disease (PD), as well as pancreatitis, hepatitis, and cancer—highlighting its potential as a promising therapeutic target." (PMID 40629421, 2025). "However, the role of miRNA-mediated regulation of VMP1 in neurodegenerative diseases, hepatitis, pancreatitis, and viral infections remains understudied." (PMID 39100095, 2024). "VMP1 was first identified as a protein responsive to pancreatitis-induced stress." (PMID 32296305, 2020). "The most likely hypothesis is that autophagy induced by pancreatitis, and mediated by overexpression of VMP1, provides the energy required of cells harboring an activating mutation in the KRAS oncogene, therefore allowing their transformation." (PMID 27833900, 2016). "Expression of the VMP1 protein, and its triggered autophagy, is therefore induced and maintained by mutation of the KRAS oncogene, which is strongly reinforced during the course of pancreatitis." (PMID 27833900, 2016). "Under acute pancreatitis-induced stress, VMP1 expression triggers zymophagy, the selective autophagy of activated zymogen granules, and mitophagy, the selective autophagy of damaged mitochondria, thus playing a protective role and avoiding the progression of pancreatitis to a severe disease." (PMID 37629161, 2023). "The vacuole membrane protein 1 (VMP1), a pancreatitis-associated protein, is a transmembrane protein with no known homologues in yeast." (PMID 25197670, 2014). "VMP1 is not detectable in human normal pancreas tissue, but its expression is activated in human pancreatitis pancreas specimens and highly colocalizes with LC3 in autophagosomes." (PMID 22550490, 2012). "Interestingly, VMP1 constitutive expression induces the formation of autophagosomes in acinar cells but does not trigger pancreatitis." (PMID 22550490, 2012).
hepatocellular carcinoma (12 papers, 2014 to 2024). A malignant tumor that arises from hepatocytes. "In hepatocellular carcinoma and colorectal cancer, low VMP1 expression is associated with advanced cancer stage and short survival, and VMP1 downregulation confers an aggressive phenotype." (PMID 34311746, 2021). "MiR-210 targets VMP1, leading to its downregulation, which is associated with a pro-tumorigenic effect across various cancers, including lung adenocarcinoma, ovarian cancer and hepatocellular carcinoma." (PMID 39100095, 2024). "The role of VMP1 in hepatic cancer, particularly in hepatocellular carcinoma (HCC), is elucidated through two key studies that are consistent in that they both show that VMP1 expression is inversely associated with the tumor malignance." (PMID 38612567, 2024). "In contrast, in hepatocellular carcinoma, VMP1 exerts a protective role by decreasing tumor spread and improving patient prognosis." (PMID 39100095, 2024). "The findings from these studies on hepatocellular carcinoma indicate a protective role of VMP1 expression in decreasing invasion and metastasis, and improving the prognosis." (PMID 38612567, 2024). "Using siRNA to silence VMP1 in HepG2 cells, a human hepatoma cell line, they found that the resulting cells have increased accumulation of neutral lipids (triglyceride and cholesterol)." (PMID 35509327, 2022). "In ovarian tumors VMP1 has been shown to be highly expressed promoting proliferation and metastasis while in colorectal and hepatocellular cancer cells high levels of VMP1 decrease proliferation, invasion and metastasis." (PMID 31442252, 2019). "Previous study showed that vmp1 plays roles in inhibition of metastasis and proliferation of hepatocellular carcinoma and an in vitro study showed that vmp1 plays important role in autophagy processes." (PMID 25950913, 2015). "Nevertheless, overexpression of VMP1 gene may decrease the proliferation, invasion and metastasis of tumor cells in colorectal and hepatocellular cancer." (PMID 34513657, 2021). "Moreover, in colorectal and hepatocellular carcinoma cells, overexpression of miR-210 has been evidenced to inhibit vacuole membrane protein 1 (VMP1) and enhance migration and invasion." (PMID 34440422, 2021). "In hypoxic hepatocellular carcinoma (HCC), vacuole membrane protein 1 (VMP1) was identified as the direct and functional downstream target of miR-210, which mediates hypoxia-induced HCC cell migration and invasion." (PMID 24909053, 2014).
colorectal cancer (11 papers, 2019 to 2024). A primary or metastatic malignant neoplasm that affects the colon or rectum. "Moreover, the HIF-1α/miR-210/VMP1 pathway is implicated in the migration and invasion of CAFs in colorectal cancer, with potential implications for colorectal cancer metastasis." (PMID 38612567, 2024). "Specifically, in colorectal cancer cell lines, the reduction in VMP1 has been shown to decrease viability in response to apoptosis inducers." (PMID 38612567, 2024). "The reviewed research works collectively indicate a significant association between miR-210 and VMP1 in the context of cancer, particularly lung adenocarcinoma, ovarian cancer, HCC, and colorectal cancer." (PMID 38612567, 2024). "Recent studies on colorectal cancer showed that miR-21 accumulated in cancer cells depleted of vmp1, indicating that vmp1 can regulate cancer cell proliferation, invasion, and metastasis through miR-21." (PMID 36012210, 2022). "The locus appears to be regulated by a complex regulatory mechanism, akin to the situation in colorectal cancer where an autoregulatory loop is between miR-21 and VMP1 and a miR-21-3p isomiR is suggested to downregulate miR-21-5p." (PMID 34797887, 2021). "Here, we found that the expression of miR-21 was negatively correlated with the expression of vacuole membrane protein-1 (VMP1) in colorectal cancer." (PMID 33318473, 2020). "We further found that disrupting the miR-21/VMP1 feedback loop will decrease the expression of miR-21, reduce the malignancy, and increase their sensitivity to 5-fluorouracil in colorectal cancer cells." (PMID 33318473, 2020). "Moreover, the authors showed that, when VMP1 expression is stimulated, miR-21 expression decreases, reducing migration and invasion, and enhancing sensitivity to 5-FU in colorectal cancer cells." (PMID 38612567, 2024). "VMP1 was identified as a direct and functional target of miR-210 in colorectal cancer." (PMID 38612567, 2024). "However, overexpression of VMP1 inhibited the metastasis, proliferation and increased their sensitivity to chemotherapeutic drug, 5-fluorouracil, in colorectal cancer cells." (PMID 37035172, 2023). "However, only VMP1 expression was significantly downregulated during the differentiation of MSCs into CAFs induced by colorectal cancer cells." (PMID 34631221, 2021). "Taken together, our results revealed a novel regulatory mechanism of miR-21 expression, and targeting the miR-21/VMP1 feedback loop may provide a new approach to inhibit miR-21 expression in colorectal cancer cells." (PMID 33318473, 2020). "A study revealed lower VMP1 expression in colorectal cancer human tissues compared to adjacent non-cancer tissues, and this reduced expression is associated with poorer patient survival." (PMID 38612567, 2024). "A negative correlation between the expression of miR-21 and VMP1 in colorectal cancer was demonstrated." (PMID 38612567, 2024). "VMP1 showed increased expression in non-cancer-adjacent tissues compared with that in colorectal cancer tissues." (PMID 36232920, 2022). "The expression of VMP1 in colorectal cancer (CRC) tissues was lower than that in adjacent non-cancer tissues, showing a negative correlation with the malignancy of the cancer." (PMID 33318473, 2020).
colon cancer (10 papers, 2013 to 2024). "Intriguingly, the regulation of VMP1 expression in cancer-associated fibroblasts differs from that in colon cancer cells." (PMID 38612567, 2024). "Furthermore, hypoxia inducible factor 1α (HIF1α) is able to trigger mitophagy by stabilization and activation of NIX protein, and is also responsible for autophagic activation through VMP1 (vacuole membrane protein 1) promoter, causing colon cancer resistance to photodynamic therapy." (PMID 30687233, 2018). "While HIF-1α induces VMP1 expression in colon cancer cells, it paradoxically decreases VMP1 expression in CAFs." (PMID 38612567, 2024). "Upon integrating the studies on VMP1 in relation to colon cancer, experimental data consistently suggest that increased VMP1 expression promotes resistance to therapy, encompassing both chemical agents and photodynamic therapy." (PMID 38612567, 2024). "On the other hand, VMP1 expression is found to be diminished in colon cancer, and its reduced expression correlates negatively with various aspects of tumor malignancy, such as proliferation and migration capacity." (PMID 38612567, 2024). "Regarding colon cancer, the role of VMP1 in malignancy appears to be more nuanced compared to its roles in other types of cancer." (PMID 38612567, 2024). "Mechanistically, VMP1 expression diminishes invasion and proliferation in colon cancer cells, which was confirmed in xenograft mouse models." (PMID 38612567, 2024). "HIF-1α induced autophagy has been shown to be reduced with down-regulation of VMP1 in human colon cancer cell lines." (PMID 35562897, 2022). "We also demonstrated that VMP1-mediated autophagy is induced by HIF-1A (hypoxia inducible factor 1 subunit alpha) in colon-cancer tumor cell lines, conferring resistance to photodynamic treatment." (PMID 32655498, 2020). "Additionally, elevated VMP1 expression in colon cancer cells can stimulate exosome secretion, facilitating resistance to 5-Fluorouracil (5-FU)." (PMID 38612567, 2024). "Furthermore, VMP1 expression is crucial for cell survival during photodynamic therapy in colon cancer cells." (PMID 38612567, 2024). "In addition, VMP1 is involved in the resistance to photodynamic therapy in colon cancer cells, in which its expression is triggered by the transcription factor hypoxia-inducible factor 1 alpha (HIF-1α)." (PMID 37629161, 2023). "VMP1 knockout in colon cancer cells promoted cell proliferation and invasion." (PMID 36232920, 2022). "Furthermore, the hypoxia-inducible factor 1-alpha (HIF-1α)/vacuole membrane protein 1 (VMP1) axis mediates therapeutic resistance in colon cancer cells." (PMID 35965522, 2022). "The expression of vmp1 in colon cancer tissues was significantly lower than that in neighboring non-cancerous tissues and was negatively correlated with the malignant degree of cancer; that is, the down-regulation of the expression of vmp1 could reduce cell adhesion and invasion ability." (PMID 36012210, 2022).
acute pancreatitis (9 papers, 2012 to 2025). An acute inflammatory process that leads to necrosis of the pancreatic parenchyma. "Additionally, VMP1 is implicated in the autophagosome membrane during the selective autophagy of activated zymogen granules (zymophagy) in an acute pancreatitis model." (PMID 38612567, 2024). "Vacuole membrane protein 1 (VMP1) is an integral endoplasmic reticulum (ER) transmembrane protein originally identified in acute pancreatitis and is now recognized as a key regulator of autophagy and related cellular processes." (PMID 40629421, 2025). "Our results demonstrate that VMP1-mediated autophagy exerts a protective effect damping pancreatic and systemic histopathological damage that occurs in experimental severe acute pancreatitis." (PMID 40243995, 2025). "It was demonstrated that VMP1 is a protein whose expression is highly and rapidly induced in response to acute pancreatitis." (PMID 38612567, 2024). "VMP1 was also involved in the cytoplasmic vacuolization of acinar cells during the early stage of acute pancreatitis." (PMID 39100095, 2024). "The characterization of the VMP1 gene has been conducted in the context of studying changes in gene expression in pancreatic acinar cells during acute pancreatitis." (PMID 38612567, 2024). "In the context of pancreatic tissue, VMP1 first gained attention within the framework of acute pancreatitis." (PMID 38612567, 2024). "In fact, we have previously found that the de-ubiquitinase probable ubiquitin carboxyl-terminal hydrolase FAF-X (USP9x) is an interactor of VMP1 in the context of the selective autophagy of zymogen granules during experimental acute pancreatitis." (PMID 37629161, 2023). "Studies have shown that in a mouse model of acute pancreatitis, after pancreatin is ubiquitinated, p62 acts as a cargo receptor to link ubiquitinated trypsin to the vmp1-autophagosome to initiate zymophagy." (PMID 35169128, 2022). "VMP1 expression is activated during acute pancreatitis in humans, and there is formation of autophagosomes where p62, LC3, and zymogen granules colocalize." (PMID 22550490, 2012). "In the search for new molecules that are differentially expressed during acute pancreatitis we found a transmembrane protein that we named Vacuole Membrane Protein 1 (VMP1)." (PMID 22550490, 2012). "Nevertheless, activated zymogen granules are ubiquitinated upon acute pancreatitis and the VMP1-mediated selective autophagic pathway sequesters these ubiquitinated granules." (PMID 22550490, 2012). "USP9x is likely to modulate zymogen granule selective engulfment during acute pancreatitis by modulating VMP1 or providing a preferential recognition signal for altered zymogen granules." (PMID 22550490, 2012). "VMP1 was first identified due to its high expression in acute pancreatitis." (PMID 40243995, 2025). "Additionally, limited report shows that VMP1 also plays a significant role in mitophagy induced by acute pancreatitis." (PMID 39100095, 2024). "Furthermore, VMP1 is identified as a mediator of mitophagy in the context of experimental acute pancreatitis." (PMID 38612567, 2024). "Moreover, VMP1 has been found to be part of the membrane of isolated autophagosomes in the context of the cellular response to acute pancreatitis." (PMID 37629161, 2023). "Also, VMP1 downregulation avoided mitochondrial degradation confirming that VMP1 expression is required for mitophagy during acute pancreatitis." (PMID 33816487, 2021). "Furthermore, VMP1 expression and zymophagy are present in human pancreas affected by acute pancreatitis." (PMID 22550490, 2012). "We use this unique tool to investigate the VMP1 pathway in autophagy during acute pancreatitis." (PMID 22550490, 2012). "During acute pancreatitis, the acinar cell activates VMP1-mediated autophagy." (PMID 22550490, 2012).
acute pancreatitis (continued). "Moreover, VMP1 downregulation (shVMP1) also significantly decreased acinar cell survival under CCK hyperstimulation showing that VMP1 expression is required to prevent acinar cell death in acute pancreatitis." (PMID 22550490, 2012).
glioma (6 papers, 2021 to 2026). A benign or malignant brain and spinal cord tumor that arises from glial cells (astrocytes, oligodendrocytes, ependymal cells). "Through the analysis of public datasets and their own patient cohort (101 patients), the authors found that VMP1 expression is inversely associated with patient survival, suggesting VMP1 as a poor prognostic predictor in glioma." (PMID 38612567, 2024). "Data analyses based on various cancer genome atlases have shown that VMP1 is upregulated in high-grade gliomas, and this is associated with a worse prognosis." (PMID 39273093, 2024). "In glioma, high VMP1 levels predict poor patient prognosis and are associated with resistance to therapy." (PMID 36499030, 2022). "VMP1 is associated with advanced glioma; therefore, we investigated the prognostic value of VMP1 in three independent cohorts." (PMID 34311746, 2021). "Our results provide insights into the pathological and biological functions of VMP1, including its roles in promoting tumor growth and progression, and support its value as a new diagnostic and prognostic biomarker for glioma." (PMID 34311746, 2021). "VMP1 overexpression was associated with advanced disease and had a poor prognosis in patients with glioma." (PMID 34311746, 2021). "A Kaplan–Meier test showed that high VMP1 expression levels are markedly associated with a poorer OS in glioma." (PMID 34311746, 2021). "To determine whether this was independent of IDH mutation, we examined our in‐house IDH‐wildtype glioma specimens and found a relative overexpression of VMP1 in GBM (WHO Grade 1–3 vs." (PMID 41589276, 2026). "Clinically, high VMP1 expression was independently associated with a dismal prognosis in glioma and could be exploited as a biomarker for predicting survival." (PMID 34311746, 2021). "Overall, these results demonstrate that VMP1 expression is significantly associated with prognosis in glioma and could be exploited as a biomarker for predicting survival." (PMID 34311746, 2021). "VMP1 was overexpressed in glioma and was associated with disease progression." (PMID 34311746, 2021). "Gene expression analyses in tumor tissues (inclusive of both IDH‐wildtype and IDH‐mutant gliomas) revealed that VMP1 was significantly overexpressed in GBM, the most malignant histological subtype." (PMID 41589276, 2026). "To gain insights into the clinical significance of VMP1 in human glioma, we examined the expression profiles of VMP1 in gliomas of different malignancy grades, histological subtypes, and molecular subtypes using data retrieved from TCGA, CGGA, and GEO." (PMID 41589276, 2026). "Driven by our initial observation of poor clinical outcomes in patients with high VMP1‐expressing GBMs, we sought to understand the role of VMP1 in glioma progression." (PMID 41589276, 2026). "Mechanistically, using VMP1 knockout (KO) glioma cell lines, the authors found that VMP1 expression is necessary for cell proliferation and to prevent apoptosis and G2/M phase cell cycle arrest." (PMID 38612567, 2024). "The results obtained from these three different experimental models are consistent, demonstrating a pro-malignant role of VMP1 expression in glioma." (PMID 38612567, 2024). "In this study, the authors used public databases to compare VMP1 expression in glioma and glioblastoma with normal brain tissue." (PMID 38612567, 2024). "There is a study that explores the role of VMP1 in the development and malignancy of glioma and glioblastoma." (PMID 38612567, 2024). "VMP1 KO significantly inhibited glioma cell proliferation, induced apoptosis and cell cycle arrest, and sensitized glioma to radiotherapy and chemotherapy by disrupting autophagic flux." (PMID 34311746, 2021). "Consistent with this, we observed the accumulation of LC3 puncta under both nutrient repletion and deprivation conditions, whereas autophagosome-lysosome formation was impaired in VMP1 KO glioma cells, resulting in incomplete autophagy." (PMID 34311746, 2021).